Y_RNA (Y RNA )
Gene: Miscellaneous RNA gene on chromosome 16 (27,722,284 to 27,722,392, reverse strand). Ensembl gene ENSG00000201371.
Homologues: Orthologues: chimpanzee Y_RNA (96% identical), macaque Y_RNA (94% identical). Paralogues in human: RNY1 (83% identical), Y_RNA (81% identical), Y_RNA (80% identical), Y_RNA (79% identical), Y_RNA (78% identical), RNY1P11 (77% identical), Y_RNA (77% identical), RNY1P5 (76% identical), Y_RNA (76% identical), RNY1P8 (75% identical), Y_RNA (75% identical), RNY1P16 (74% identical), and 93 more.